IL9 (interleukin 9)
Diseases named in the same sentence as IL9 in open-access papers (continued):
Sharing a sentence is not in itself a finding about the gene and the disease.
cystic fibrosis (6 papers, 2006 to 2024). Autosomal recessive disorder caused by pathogenic variants in the CFTR gene (cystic fibrosis transmembrane conductance regulator), which encodes a chloride and bicarbonate channel expressed in epithelial cells, and follow the diagnosis criteria. "In addition, we have previously shown that a non-synonymous IL-9 polymorphism (rs2069885), known to be associated with lung function and sensitization, correlates with high IgE levels in female cystic fibrosis patients." (PMID 30515173, 2018). "Indeed, we have shown that IL-9 is overproduced in female expectorates of cystic fibrosis patients and a genetic variant of IL-9 showed a sex-specific association with IgE levels in female patients." (PMID 30515173, 2018). "Overproduction of IL-9 is observed in expectorates from cystic fibrosis patients, and a sex-specific variant of IL-9 is predictive of allergic reactions in female patients." (PMID 28090087, 2017). "In patients with cystic fibrosis, IL-9 signalling is increased." (PMID 28090087, 2017). "Correspondingly, the administration of antibodies that neutralize IL-9 protected mice from both IPF and cystic fibrosis." (PMID 38879568, 2024). "While the administration of IL-9 neutralizing antibody protects mice from IPF and cystic fibrosis." (PMID 32676074, 2020).
diffuse large B-cell lymphoma (6 papers, 2016 to 2022). "Recently, the study has showed that famotidine treatment resulted in significant downregulation of LDH, TGF-β, bFGF and IL-9, respectively, and significant upregulation of Caspase-3 expression in diffuse large B-cell lymphoma." (PMID 34686215, 2021). "It has been reported that IL-9 promotes lymphoma cell survival and drug resistance in diffuse large B cell lymphoma (DLBCL)." (PMID 32228589, 2020). "Indeed, elevated serum IL-9 was found in the patients with metastatic breast cancer or diffuse large B-cell lymphoma (DLBCL)." (PMID 28894450, 2017). "Studies have shown that IL-9 levels are significantly increased in the serum of patients with diffuse large B-cell lymphoma (DLBCL), and IL-9 levels are correlated with the DLBCL prognostic index." (PMID 35211408, 2022). "Wang and colleagues reported elevated serum levels of IL-9 in B cells from non-Hodgkin’s lymphoma and diffuse large B-cell lymphoma (DLBCL) patients, along with high levels of IL-9R expression in tumoral tissues that correlate with adverse prognostic markers of the disease." (PMID 34944921, 2021).
gastric cancer (6 papers, 2020 to 2025). A primary or metastatic malignant neoplasm involving the stomach. "In a mouse gastric cancer model, increased TGF-β and IL-4 promoted IL-9 secretion by Th9 cells, inhibiting tumor-associated inflammation and metastasis." (PMID 40909266, 2025). "In gastric cancer, high IL-9 expression correlates with improved patient survival, and recombinant IL-9 augments the efficacy anti-PD-1 immunotherapy." (PMID 41030439, 2025). "For instance, IL9 inhibited the proliferation of the gastric cancer cell line SGC-7901 in vitro through the activation of adaptive or innate immune responses." (PMID 35433683, 2022). "A positive feedback loop system has been reported through TGF-β1 and IL-9 in gastric carcinoma, with Tregs promoting MC proliferation via IL-9 and MCs inducing increased Tregs cells via TGF-β1 secretion." (PMID 35682552, 2022). "IL-9 also exerts anti-tumoral activity in gastric cancer, as demonstrated by the fact that it inhibits both the proliferation and migration of the gastric cancer cell line SGC-7901 in vitro." (PMID 34944921, 2021). "Moreover, Th9 cells and Th9 cell-derived IL-9 also have a strong ability to inhibit tumor metastasis and growth in metastatic lung cancer and gastric cancer in nude mice." (PMID 32228589, 2020). "Moreover, IL-9 can inhibit the proliferation and migration of the gastric cancer cell line SGC-7901 in vitro." (PMID 32228589, 2020). "In nude mice, IL-9 can significantly inhibit the growth of gastric cancer." (PMID 32228589, 2020). "Tregs have been shown to mediate the recruitment and functions of MCs via IL-9 production in vivo and in NTS and gastric carcinoma models." (PMID 35682552, 2022).
gastritis (6 papers, 2020 to 2025). Inflammation of the stomach. "Some studies have reported that the proportion of Th9 cells in patients with H. pylori - associated gastritis and peptic ulcer is significantly higher than that in healthy individuals, and the serum level of IL-9 also increases remarkably." (PMID 40552296, 2025). "We demonstrated in this study that more IL-9 was secreted in H. pylori-positive gastritis patients, and IL-9 level was positively associated with mucosal inflammation." (PMID 33777009, 2021). "Our observations suggested the association of IL-9 with mucosal inflammation in H. pylori-positive gastritis." (PMID 33777009, 2021). "Detailed analysis of its mechanism revealed that the OX40–OX40L pathway promotes mucosal MAIT cell proliferation and IL‐9 production in H. pylori‐positive gastritis." (PMID 41179703, 2025). "The frequency of Tc9 cells, but not Th9 cells, was increased in both acute and chronic Helicobacter pylori-induced gastritis, but IL-9 was elevated only in chronic active gastritis patients." (PMID 36154925, 2023). "Taken together, we found that MAIT cells of H. pylori gastritis patients secreted more IL-9 compared to healthy controls, indicating the necessity to further explore the role of IL-9 producing MAIT cells in H. pylori infection-induced gastritis." (PMID 33777009, 2021). "In this study, we investigated the potential role of IL-9 producing MAIT cells regulated by OX40/OX40L signal in H. pylori-induced gastritis." (PMID 33777009, 2021). "We found that OX40 was highly up-regulated in the gastric mucosa of gastritis patients, consistent with the elevated level of IL-9 and increased number of MAIT cells." (PMID 33777009, 2021). "IL-9 level in the gastric mucosa of gastritis patients was positively correlated with mucosal inflammation, represented by up-regulated gene expression of pro-inflammatory cytokines and mucus-secreting related molecules." (PMID 33777009, 2021). "This indicates that in gastritis induced by H. pylori infection, Th9 cells are activated and their numbers increase, accompanied by a corresponding increase in the secretion of their characteristic cytokine, IL-9." (PMID 40552296, 2025). "Serum examination revealed an increased level of IL-9 in gastritis patients." (PMID 33777009, 2021). "Taken together, our research investigated the promoting effect of OX40-OX40L pathway on mucosal MAIT cell proliferation and IL-9 production during H. pylori-positive gastritis, providing potential strategies for clinical treatment of H. pylori-induced gastritis." (PMID 33777009, 2021). "Taken together, we elucidated that OX40/OX40L axis promoted mucosal MAIT cell proliferation and IL-9 production in H. pylori-induced gastritis, which may provide potential targeting strategies for gastritis treatment." (PMID 33777009, 2021). "Thus we hypothesized that IL-9+ MAIT cells might regulate the mucosal inflammation in H. pylori-mediated gastritis." (PMID 33777009, 2021). "Meanwhile, it has been proved that OX40 can induce IL-9 production by Th9 cells, which both inspired us to explore the role of OX40 in mucosal resident MAIT cells of gastritis patients." (PMID 33777009, 2021). "We next isolated MAIT cells from the mucosa of H. pylori gastritis patients and treated MAIT cells with recombinant OX40L protein to activate OX40 expressed on MAIT cells and determined the production of IL-9." (PMID 33777009, 2021). "Here we identified OX40, a co-stimulatory molecule mainly expressed on T cells, as a critical regulator to promote proliferation and IL-9 production by MAIT cells and facilitate mucosal inflammation in H. pylori-positive gastritis patients." (PMID 33777009, 2021). "Either OX40 or OX40L blockage inhibited MAIT cell proliferation and IL-9 production, indicating the critical role of the OX40/OX40L signal in MAIT cell activation and IL-9 secretion in H. pylori-induced gastritis." (PMID 33777009, 2021).
gastritis (continued). "We identified a group of Th9-like MAIT cells in the gastric mucosa of gastritis patients with the ability to secrete IL-9, and elucidated that OX40/OX40L axis promoted proliferation and IL-9 production of MAIT cells." (PMID 33777009, 2021). "To further explore the relevance of IL-9-producing MAIT cells with H. pylori-mediated gastric mucosal inflammation, we analyzed the correlation between the percentage of IL-9+ MAIT cells and inflammatory indicators exhibited in H. pylori gastritis patients." (PMID 33777009, 2021). "Although the levels of IL-5, IL-6, IL-9, IL-10, IL-13, and IL-21 were higher in patients with gastritis than Hp- group, this increase was not significant." (PMID 39807418, 2024). "To explore the relation of IL-9 with MAIT cells, we further analyzed the percentage of IL-9+ MAIT cells and the correlation between the percentage of MAIT cells and serum IL-9 level in H. pylori gastritis patients." (PMID 33777009, 2021). "Since OX40 promoted IL-9 production of MAIT cells, we then examined whether OX40 facilitated MAIT cell activation in H. pylori-induced gastritis, as what we found in T2D patients." (PMID 33777009, 2021). "Furthermore, flow cytometry examination also demonstrated the increased percentage of IL-9+ CD161+ cells (gated in TCRα7.2+ T cells) and IL-9+ MAIT cells (gated in TCRα7.2+ CD161+ T cells) in the gastric mucosa of H. pylori-positive gastritis patients." (PMID 33777009, 2021). "Patients with atrophic gastritis presented significant lower levels of IL-2, IL-9, IL-6, TGF-β, GM-CSF, IL-17 and ET-1 (p < 0.005) compared to patients without gastritis." (PMID 32947843, 2020). "Patients with atrophic gastritis showed significant lower levels of many cytokines (IL-2 (p = 0.036), IL-9 (p = 0.001), IL-6 (p = 0.038), and TGF-β (p = 0.015) GM-CSF (p = 0.001), IL-17 (p = 0.001) and ET-1 (p = 0.001)) compared to patients without gastritis." (PMID 32947843, 2020).
ischemic stroke (6 papers, 2015 to 2023). A stroke disorder caused by obstruction of blood flow to the brain, due to thrombotic (local blood clot formation) or embolic (due to a blood clot or other material traveling from another site) event. "Furthermore, another study reported that higher levels of IL-1β and lower levels of its antagonist IL-1ra and anti-inflammatory cytokine IL-9 in the acute phase of ischemic stroke were associated with PSF in 6 and 12 months." (PMID 26166952, 2015). "Thus, IL‐9 has been verified as a potential pathogenic factor in ischaemic stroke." (PMID 33314611, 2021). "Li's study showed that the serum IL-4, IL-5, IL-7, and IL-9 levels decreased in the ischemic stroke patients with poor outcome." (PMID 36875689, 2023). "Anti-IL-9-neutralizing antibody can ameliorate ischemic stroke injury partially by alleviating the destruction of the BBB via down-regulation of astrocyte-derived VEGF-A." (PMID 35173738, 2022). "G-CSF has been shown to be neuroprotective in ischemic stroke models by inducing anti-apoptotic pathways, and IL-9 is known to promote cell proliferation and inhibit apoptosis." (PMID 27596278, 2016).
ZIKV infection (6 papers, 2018 to 2021). "ZIKV infection increases the levels of a series of cytokines (IL-1α, IL-6, IL-9, IL-10, IL-12p70, and IFN-γ) and chemokines (CCL2, CCL3, CCL4, CCL5, CCL11, and CXCL1) in mouse brain." (PMID 34399779, 2021). "Cytokine profiles in acute ZIKV infections were estimated using a multiplex bead analysis assay which measured interleukin (IL) 1β, IL-2, IL-4, IL-6, IL-8, IL-9, IL-10, IL-13, and IL-17." (PMID 30682026, 2019). "For example, Zika virus infection was associated with an increased secretion of IL2, IL4, IL13, and IL9 cytokines." (PMID 29937515, 2018). "These cytokines have diverse functional patterns such as Th1 (IFN-γ), Th2 (IL-5), and Th9 (IL-9) cells, suggesting the activation of these T helper lymphocyte subsets in acute ZIKV infection." (PMID 29774022, 2018). "Cytokines and chemokines with higher levels during acute ZIKV infection were IP-10, RANTES, IFN-γ, IL-9, IL-7, IL-1ra, and IL-5, involving innate and adaptive immune responses." (PMID 29774022, 2018). "Interestingly, depletion of CD14+ monocytes and ZIKV infection did not affect the levels of epidermal growth factor (EGF), interleukin 9 (IL-9), IL-17A, macrophage inflammatory protein 1α (MIP-1α), and MIP-1β." (PMID 29600283, 2018).
lupus nephritis (5 papers, 2015 to 2024). Glomerulonephritis in the context of systemic lupus erythematosus. "Thus, the aim of this research is to determine the plasma levels of IL-25 and Th2-associated cytokines (IL-4, IL-5, IL-6, IL-9, IL-10, IL-13) in SLE patients with (SLE-LN) and without lupus nephritis." (PMID 31697750, 2019). "IL-9 and IL-10 showed a significant positive correlation with IL-25 in 64 patients of SLE with and without lupus nephritis." (PMID 31697750, 2019). "IL-9 and IL-10 showed a significant positive correlation with IL-25 in all 17 SLE patients with lupus nephritis, whereas a significant negative correlation was observed with IL-5 and IL-6." (PMID 31697750, 2019).
nematode infection (5 papers, 2014 to 2025). "Reciprocal neutralization of endogenous IL-9 that was achieved by vaccination against IL-9 before nematode infection rendered resistant C57BL/6 mice susceptible for T. muris infection." (PMID 24516385, 2014). "Furthermore, the administration of anti-IL-9 to mice that typically expel worms demonstrated a significant impact, making these mice susceptible to nematode infection." (PMID 39199394, 2024). "This indicates that IL-9 plays a pivotal role in susceptibility to nematode infection." (PMID 39199394, 2024). "IL-9 was initially thought to be a Th2 cytokine because increased IL-9 production was observed alongside IL-4, IL-5, and IL-13 in animal models of nematode infection and allergic inflammation." (PMID 40489251, 2025). "The observation that mice, which typically expel worms, become vulnerable following the administration of anti-IL-9 indicates that IL-9 plays a crucial role in nematode infection." (PMID 39199394, 2024). "The particular importance of IL-9 and IL-9-mediated mast cell activation for host defense during gastrointestinal nematode infection, however, depends on the nematode species and the genetic background of the host." (PMID 24516385, 2014). "This could explain why hyperplasia of the goblet cells occurs in nematode infections and the hyperplasia that might be induced by IL-9." (PMID 28404797, 2017).
periodontal disease (5 papers, 2020 to 2024). "Although the role of IL-9 in the periodontal diseases pathogenesis is unclear, some studies have shed light on its role in other chronic inflammatory diseases." (PMID 33218047, 2020).
psoriatic arthritis (5 papers, 2017 to 2025). Joint inflammation associated with psoriasis. "Recently, elevated levels of IL-9 have been documented in arthritic conditions such as psoriatic arthritis (PsA) and RA." (PMID 34638736, 2021). "For example, a high level of IL-9 has been detected in the peripheral blood and synovial fluid of patients with RA and patients with psoriatic arthritis (PsA), and the level of IL-9 in the synovial fluid is higher than that in the peripheral blood for RA and PsA patients." (PMID 28424692, 2017).
schizophrenia (5 papers, 2012 to 2025). A major psychotic disorder characterized by abnormalities in the perception or expression of reality. "Our results indicate some evidence for a potential causal role of a number of immunological proteins/traits in schizophrenia including IL-6, sIL-2Rα, IL-9, MCP-1 and BDNF." (PMID 34280516, 2021). "Genetically-predicted sIL-2Rα (OR=1.07; 95% C.I., 1.01-1.12) and IL-9 (OR=1.06; 95% C.I., 1.01-1.11) were associated with increased schizophrenia risk." (PMID 34280516, 2021). "We found weak evidence for potential causal associations of MCP-1 and IL-9 with schizophrenia." (PMID 34280516, 2021). "IL-9 has been found to be associated with multi-episode schizophrenia in a cross-sectional study." (PMID 34280516, 2021). "First, our results indicate some evidence in support of a potential causal relationship between IL-6, IL-9, MCP-1, sIL-2Rα, and BDNF with schizophrenia, although only the association with IL-6 survived correction for multiple testing." (PMID 34280516, 2021). "Genetic variants in the 5q region have previously been found to be associated with schizophrenia (e.g., IL3, IL4, IL9, NEUROG1)." (PMID 22723893, 2012). "Studies have shown that patients with schizophrenia exhibitelevated levels of monocytes, neutrophils, and C-reactive protein (CRP).Additionally, various cytokines (e.g., monocyte chemoattractant protein-1,IL-1β, IL-5, IL-6, IL-9 and TNF-α) have been reported to beupregulated in schizophrenia." (PMID 40926813, 2025).
T-cell lymphoma (5 papers, 2013 to 2024). "A recent study also showed that nucleolin modulates Interleukin-9 (Il9) expression in T-cell lymphoma cells." (PMID 25057429, 2013). "For example, IL-9 was specifically expressed by nasal NK/T-cell lymphoma cell lines, where it acted as an autocrine growth factor, suggesting that the IL-9 signaling pathway may be a new therapeutic target for NK/T-cell lymphoma." (PMID 24722378, 2014). "Importantly, IL-9 mRNA was not expressed in other EBV-negative NK-cell and T-cell lymphoma/leukemia cell lines, suggesting that EBV may be related to the IL-9 expression of SNK-6 and SNT-8." (PMID 34202088, 2021).
thymic lymphomas (5 papers, 2014 to 2022). "By generating transgenic mice overexpressing the Il9 gene, Renauld and colleagues found that a small proportion of IL-9 overexpressing mice developed thymic lymphomas, suggesting that IL-9 supports the development of T cell tumors." (PMID 27832300, 2017). "The action of IL-9 on thymocytes in vitro is interesting in view of the development of thymic lymphomas." (PMID 25373337, 2015). "In IL-9 transgenic mice it has been observed that IL-9 is a major anti-apoptotic factor for thymic lymphomas." (PMID 25373337, 2015). "In vitro, IL-9 was able to stimulate JAK3-dependent survival of ALK+ anaplastic large-cell lymphoma cells and protect thymic lymphoma cells from dexamethasone-induced apoptosis." (PMID 24722378, 2014). "However, we previously showed that IL-9 alone did not promote thymocyte proliferation, while in combination with IL-7, it synergistically enhances cell proliferation, and may activate the JAK-STAT pathway during thymic lymphoma development." (PMID 35336821, 2022).
acute respiratory distress syndrome (4 papers, 2012 to 2025). Progressive and life-threatening pulmonary distress in the absence of an underlying pulmonary condition, usually following major trauma or surgery. "Elevated levels of pro-inflammatory cytokines and chemokines (e.g., TNFα, IFNγ, IL-1, IL-6, IL-8, IL-9, IL-12 IL-15, and IL-17) have been found, up to 10 days after the onset of symptoms, in the plasma of patients with acute respiratory distress syndrome (ARDS) caused by influenza A/H1N1." (PMID 32219005, 2019). "Elevated levels of pro-inflammatory cytokines and chemokines (e.g., TNFα, IFNγ, IL-1, IL-6, IL-8, IL-9, IL-12 IL-15, and IL-17) have been found, up to ten days after the onset of symptoms, in the plasma of patients with acute respiratory distress syndrome (ARDS) caused by influenza A/H1N1." (PMID 23148654, 2012).